RNU6-17P (RNA, U6 small nuclear 17, pseudogene)
Synonyms: RNU6-17
Gene: Small nuclear RNA gene on chromosome 15 (30,254,402 to 30,254,508, reverse strand). Ensembl gene ENSG00000206972.
Homologues: Orthologues: rat U6 (100% identical), dog U6 (96% identical), mouse Gm23947 (94% identical), guinea pig U6 (90% identical), pig U6 (87% identical). Paralogues in human: RNU6-18P (100% identical), RNU6-1 (99% identical), RNU6-12P (99% identical), RNU6-13P (99% identical), RNU6-2 (99% identical), RNU6-32P (99% identical), RNU6-3P (99% identical), RNU6-4P (99% identical), RNU6-5P (99% identical), RNU6-6P (99% identical), RNU6-9 (99% identical), RNU6-25P (98% identical), and 1289 more.